UGT1A5 (UDP glucuronosyltransferase family 1 member A5)
Description:
[Isoform 1]: UDP-glucuronosyltransferase (UGT) that catalyzes phase II biotransformation reactions in which lipophilic substrates are conjugated with glucuronic acid to increase the metabolite's water solubility, thereby facilitating excretion into either the urine or bile. Essential for the elimination and detoxification of drugs, xenobiotics and endogenous compounds. Involved in the glucuronidation of the AGTR1 angiotensin receptor antagonist zolarsatan, a drug which can inhibit the effect of angiotensin II. [Isoform 2]: Lacks UGT glucuronidation activity but acts as a negative regulator of isoform 1.
Synonyms: UDPGT 1-5; UGT1E; UDPGT
Tractability: Antibody: UniProt predicts a signal peptide or a membrane-spanning region.
Safety:
Unwanted effects reported when the protein is acted on. In parentheses: how it was acted on, where the effect was seen, and who reports it.
adverse reactions (source: ClinPGx)
hand-foot syndrome (source: ClinPGx)
hyperbilirubinemia (source: ClinPGx)
hyperprolactinemia (source: ClinPGx)
liver failure (source: ClinPGx)
nephrolithiasis (source: ClinPGx)
neutropenia (source: ClinPGx)
Gene: Protein-coding gene on chromosome 2 (233,712,907 to 233,773,300, forward strand). Ensembl gene ENSG00000288705.
Subcellular location: Endoplasmic reticulum membrane
Pathways (Reactome):
Drug ADME: Aspirin ADME
Metabolism: Glucuronidation
Gene Ontology:
Molecular function: glucuronosyltransferase activity; enzyme binding; enzyme inhibitor activity; protein heterodimerization activity; protein homodimerization activity; UDP-glycosyltransferase activity
Biological process: cellular response to glucocorticoid stimulus; estrogen metabolic process; flavone metabolic process; liver development; monocarboxylic acid metabolic process; steroid metabolic process
Cellular component: endoplasmic reticulum; endoplasmic reticulum membrane
Genetic constraint (gnomAD): Loss-of-function variants: 29 observed, 42.26 expected, observed/expected ratio (o/e) 0.69, 90% interval 0.51 to 0.94. The upper end of that interval is the gene's LOEUF score, 0.94, which puts it in group 3 of 6, group 1 being the genes least tolerant of losing a copy. Missense variants: 678 observed, 703.8 expected, observed/expected ratio (o/e) 0.96, 90% interval 0.9 to 1.03. Synonymous variants: 257 observed, 272.44 expected, observed/expected ratio (o/e) 0.94, 90% interval 0.85 to 1.05.
Homologues: Orthologues: rabbit UGT1-6 (78% identical), mouse Ugt1a2 (74% identical), mouse Ugt1a5 (74% identical), zebrafish ugt2a7 (40% identical), zebrafish ugt2b5 (39% identical), zebrafish ugt2b1 (39% identical), zebrafish si:ch73-334d15.1 (38% identical), zebrafish ugt5a2 (36% identical), zebrafish ugt5b4 (36% identical), zebrafish ugt5a1 (35% identical), zebrafish ugt5g1 (35% identical), zebrafish ugt5c1 (35% identical), and 96 more. Paralogues in human: UGT1A3 (95% identical), UGT1A4 (93% identical), UGT1A1 (73% identical), UGT1A9 (69% identical), UGT1A8 (68% identical), UGT1A10 (68% identical), UGT1A7 (68% identical), UGT1A6 (67% identical), UGT2B4 (44% identical), UGT2B17 (43% identical), UGT2B10 (43% identical), UGT2B15 (43% identical), and 9 more.
Diseases named in the same sentence as UGT1A5 in open-access papers:
UGT1A5 is named in the same sentence as 4 diseases in open-access papers, as found by Europe PMC text mining. Sharing a sentence is not in itself a finding about the gene and the disease. The quoted sentences say what the papers report.
cholestasis (1 paper, 2023). Impairment of the bile flow caused by obstruction within the liver, or outside the liver in the bile duct system. "In the cholestasis mice model, the UGT1A5 expression level changed significantly as well." (PMID 37622118, 2023).
cancer (2 papers, 2017 to 2024). A tumor composed of atypical neoplastic, often pleomorphic cells that invade other tissues. "The majority of the genes synergistically upregulated by inhibition of both PD-L1 and TGF-β were associated with metabolic pathways (Nqo1, Hmgsc1, Sult1a1, Pla2g7, Ugt1A5, Ugt2B5, Abcb1a), that enhance cancer cell proliferation, invasion, and metastasis (Fig-6D)." (PMID 38516270, 2024).
UGT1A5 also shares sentences with these, for which no sentence is quoted: cholelithiasis (1 paper); metabolic disorders (1).